TSC1 (TSC complex subunit 1)
Diseases named in the same sentence as TSC1 in open-access papers (continued):
Sharing a sentence is not in itself a finding about the gene and the disease.
tuberous sclerosis (continued). "One of the neurogenetic disorders that are associated with seizures and autistic behaviors is tuberous sclerosis complex (TSC) caused by mutations in TSC1 or TSC2." (PMID 30683131, 2019). "LAM is caused by inherited (TSC-LAM) or acquired (sporadic or S-LAM) mutations of the tumor suppressor tuberous sclerosis complex (TSC) genes TSC1 (hamartin) or TSC2 (tuberin)." (PMID 30573768, 2019). "Tuberous sclerosis, which is a monogenic disease and causing cystic lesions and angiomyolipomas in kidneys as well as other multisystemic abnormalities, mutations in TSC1 or TSC2 leads hyperactivation of mTOR and mTOR inhibitors might be the first effective treatment for these patients." (PMID 31658846, 2019). "And they are often associated with tuberous sclerosis complex (TSC), which is an autosomal dominant genetic disease because of losses of TSC1 (9q34) or TSC2 (16p13.3) genes." (PMID 30111336, 2018). "Tuberous sclerosis (TSC) is an inherited tumour syndrome caused by mutations in TSC1 or TSC2 that lead to aberrant activation of mTOR." (PMID 28938574, 2017). "The genes Tsc1 and Tsc2 got their names from a severe autosomal dominant disorder, called Tuberous sclerosis complex (TSC), resulting from mutations in one or two of these genes." (PMID 26795955, 2016). "Typically rhabdomyomas are multiple lesions and usually regress spontaneously but are often associated with tuberous sclerosis complex (TSC), an autosomal dominant multisystem disorder caused by mutations in either of the two genes, TSC1 or TSC2." (PMID 24884933, 2014). "Inactivating mutations in either TSC1 or TSC2 result in Tuberous Sclerosis Complex (TSC), characterized by abnormal cortical development and seizures." (PMID 22567115, 2012). "Tuberous sclerosis complex (TSC) is an inherited disease caused by a heterozygous germ line mutation of either the Tsc1 or Tsc2 gene that is manifested in early childhood." (PMID 22848848, 2012). "Tuberous sclerosis (TSC) related tumors are characterized by constitutively activated mTOR signaling due to mutations in TSC1 or TSC2." (PMID 21915260, 2011). "Another example is tuberous sclerosis (TSC), a genetic disorder resulting from mutation in one of the two tumor suppressor genes, TSC1 or TSC2, that often give rise to multiple neurological deficits such as epilepsy, mental retardation and autism." (PMID 20230616, 2010). "While neurological dysfunction in patients with tuberous sclerosis is clearly linked to structural brain abnormalities in the central nervous system, recent work has provided evidence that TSC1/2 may affect neural development by altering neuronal morphology and function." (PMID 17440611, 2007). "Genetic testing results indicated no pathogenic or likely pathogenic variants in the coding and surrounding regions of the TSC1 and TSC2 genes, which are linked to tuberous sclerosis and LAM." (PMID 40641534, 2025). "Mutations in TSC1 or TSC2 genes disrupt the function of TSC1-TSC2 complex, leading to mTORC1 hyperactivation, which is thought to cause tuberous sclerosis complex." (PMID 39901197, 2025). "Four individuals were diagnosed with tuberous sclerosis: patient 15 with a SNV in the TSC1 gene, patient 16 with a SNV in the TSC2 gene, and patients 17 and 18 with deletions that also encompassed the TSC2 gene." (PMID 40428344, 2025). "Genetic testing for mutations in the TSC1 and TSC2 genes is important, given that LAM has been associated with tuberous sclerosis." (PMID 40761985, 2025). "Mutations in genes such as TSC1, TSC2, and MTOR itself, which lead to hyperactivation of the mTOR pathway, are central to the pathogenesis of diseases like tuberous sclerosis complex (TSC) and certain forms of cancer." (PMID 40358185, 2025). "In the context of inherited genetic syndromes, neurofibromatosis type 1 and tuberous sclerosis show autosomal dominant mutations that inactivate suppressor genes NF1, TSC1 and TSC2." (PMID 40002868, 2025).
tuberous sclerosis (continued). "The tuberous sclerosis complex, comprised of TSC1, TSC2 and TBC1D7 components, negatively regulates mTORC1 through Rheb GAP activity." (PMID 38746323, 2024). "More exciting, however, was a case (case 11) clinically diagnosed with Tuberous Sclerosis, and for which previous extensive testing of the TSC1 and TSC2 genes was unremarkable." (PMID 38540401, 2024). "Pulmonary LAM has been identified as being associated with tuberous sclerosis complex (TSC) in its pulmonary manifestation (TSC-LAM), a multisystem genetic disorder resulting from mutations in either the TSC1 or TSC2 genes." (PMID 38596252, 2024). "TSC1 and TSC2 respectively encode for the hamartin (TSC1) and tuberin (TSC2) proteins, which together form the tuberous sclerosis complex." (PMID 39456169, 2024). "Mutations of TSC1 and TSC2 genes cause classical Tuberous Sclerosis Complex (TSC), a neurocutaneous disorder characterized by a tendency to develop hamartias, hamartomas, and other tumors." (PMID 37063680, 2023). "The genes TSC1 and TSC2 encode tumor suppressors and their loss of function leads to the inherited hamartomas syndrome tuberous sclerosis complex (TSC)." (PMID 36627370, 2023). "TSC1 and TSC2 display an autosomal dominant pattern of inheritance, which means that in a tuberous sclerosis patient, a single pathogenic variant can be considered causative." (PMID 37834053, 2023). "Dysregulated mTORC1 signalling is also well documented in the inherited condition Tuberous Sclerosis Complex (TSC), due to loss of function mutations in the upstream mTORC1 regulators, TSC1 and TSC2." (PMID 37337371, 2023). "The other highly ASD-penetrant heterozygous mutations in the TSC1 or TSC2 genes, key regulators of mTOR signaling, cause tuberous sclerosis (TSC)." (PMID 35055151, 2022). "Mutations in TSC1 or TSC2 (hamartin and tuberin, respectively) lead to tuberous sclerosis complex, a tumor suppressor syndrome characterized by overgrowth in multiple organs including the brain, resulting in intellectual disability, autism, and epilepsy." (PMID 35250833, 2022). "It is well known that functional mutations of tuberous sclerosis complex 1(TSC-1), a negative regulator of mTOR, can cause TSC, and the affected patients may require organ transplantation after organ failure." (PMID 36186130, 2022). "Tuberous sclerosis, a disease in which mTORC1 is over-activated by TSC1 or TSC2 deletion, which leads to the formation of a wide range of benign tumors, is also direct evidence that mTORC1 plays a key role in tumorigenesis." (PMID 35558559, 2022). "Mutations in TSC1 and TSC2 are known to cause syndromic autism, known as tuberous sclerosis, with high rates of comorbid ASD." (PMID 36143905, 2022). "An increasing number of patients with TSC have undergone TSC1/TSC2 genetic testing since the presentation of the genetic diagnosis of TSC at the 2012 International Tuberous Sclerosis Complex Consensus Conference." (PMID 35246210, 2022). "Neurodevelopmental delays along with cognitive impairments are thought to stem from synaptic structure and function aberrations that are characteristic of ASDs and monogenic IDs such as FXS, RTT, tuberous sclerosis (TSC caused by mutations in the TSC1/TSC2 complex)." (PMID 34566717, 2021). "Tsc2+/− and Tsc1 homozygous mutant mice (a model of tuberous sclerosis), were treated with rapamycin, rescuing spatial learning and context discrimination deficits together with neurological findings." (PMID 34200511, 2021).
tuberous sclerosis (continued). "The TSC1 and TSC2 genes are tumor suppressor genes, and mutations of either TSC1 or TSC2 lead to the tuberous sclerosis syndrome, which is a multisystem disorder characterized by benign tumors in many organs, including lung, heart, kidney, and brain." (PMID 33445779, 2021). "For this a neuronal Tsc1 cKO mouse model of tuberous sclerosis was characterized to determine the effect on tau protein levels in the brain." (PMID 34127790, 2021). "Increased AKT/mTOR activity is consistent with deficiencies of FMR1, TSC1/2, or PTEN found in Fragile X, tuberous sclerosis, and Cowden syndrome." (PMID 33482199, 2021). "In tuberous sclerosis complex (TSC), Tsc2 mutations are associated with more severe disease manifestations than Tsc1 mutations and the role of extracellular vesicles (EVs) in this context is not yet studied." (PMID 34262466, 2021). "Tuberous Sclerosis, also known as Tuberous Sclerosis Complex (TSC) is a rare genetic disorder caused by germline inactivating mutations in either the TSC1 or TSC2 genes." (PMID 32087199, 2020). "Mutations in the mTOR inhibitor genes, TSC1 and TSC2, have been shown to cause overactivity in the mTOR pathway, thus leading to epilepsy in patients with tuberous sclerosis." (PMID 33192961, 2020). "In 2012, the Tuberous Sclerosis Complex Surveillance and Management recommendations were updated to include the identification of a heterozygous pathogenic variant in either TSC1 or TSC2 by molecular genetic testing as meeting criteria for a definitive diagnosis of TSC." (PMID 32383331, 2020). "Our research indicated that the TSC1 mutation c.1550_1551del triggered aberrant splicing and NMD simultaneously, resulting in decrease in hamartin for the development of the tuberous sclerosis complex." (PMID 32735081, 2020). "MINI‐Gene and function validation assay demonstrated that the novel TSC1 mutation triggered aberrant splicing and NMD simultaneously, caused decrease of hamartin, then resulted in tuberous sclerosis complex." (PMID 32735081, 2020). "Upregulation of mTOR signaling due the inactivation of TSC1/2 (Tuberous Sclerosis 1 and 2) is believed to be a key oncogenic driver in this disease." (PMID 33180365, 2020). "Our study demonstrated that the novel TSC1 frameshift mutation (TSC1 c.1550_1551del) trigger aberrant splicing and NMD simultaneously, causing decrease of hamartin, then, leading to tuberous sclerosis complex formation." (PMID 32735081, 2020). "Tuberous sclerosis (TSC) tumor suppressor complex (TSC1/TSC2) indirectly inhibits mTORC1 activity by negatively regulating the activity of Rheb via the GTPase-activating protein (GAP) activity of TSC2." (PMID 32974004, 2020). "Another condition, tuberous sclerosis (TSC), involves mutation of either TSC1 and TSC2 genes that codes for proteins hamartin and tuberin, which act as tumor suppressors that regulate cell growth and the mTORC1 complex." (PMID 33519379, 2020). "An association with tuberous sclerosis (TSC-LAM complex) is known, with mutations of two known genes (TSC1 and TSC2) found in these cases." (PMID 32471113, 2020). "Four FCD2b cases had a somatic variant in TSC1/TSC2 genes; one FCD2a case had a germline pathogenic variant in TSC2 and was subsequently diagnosed with a mild form of tuberous sclerosis complex." (PMID 31444548, 2019). "These mouse models have shown that dysregulation of the mTOR signaling pathways, induced by Tsc1 and Tsc2 inactivation, results in a Tuberous Sclerosis-like phenotype." (PMID 31245336, 2019). "The intrinsic GTPase of Rheb is activated by Tsc1 and Tsc2, which are the gene products responsible for tuberous sclerosis complex (TSC)." (PMID 31454940, 2019). "Genes that are part of this pathway have previously been implicated in various neurological diseases such as Parkinson’s disease (PARK2), frontotemporal dementia (MAPT), neurofibromatosis 2 (NF2), tuberous sclerosis (TSC1)." (PMID 30258056, 2018).
tuberous sclerosis (continued). "Loss of function of Tuberous Sclerosis Complex 1 (TSC1) or TSC2 in the setting of the genetic condition, Tuberous Sclerosis Complex, activates mTORC1 and downregulates the basal level autophagy in dividing cells." (PMID 29540819, 2018). "We also compared aspects of our patient's condition with the clinical features of tuberous sclerosis (TSC), which is an autosomal neurocutaneous syndrome caused by mutations in the TSC1/TSC2 genes." (PMID 30332768, 2018). "Changes in the TSC1/2 gene responsible for tuberous sclerosis ultimately results in mTOR activity, leading to epilepsy." (PMID 28966575, 2017). "We chose to study two forms of hereditary kidney cancer, i.e., von Hippel-Lindau disease (VHL) and Tuberous Sclerosis Complex (TSC), due to germline mutations of VHL or TSC1/2, respectively." (PMID 27682873, 2017). "Tuberous sclerosis complex is a multisystem disease in which inactivation of the TSC1 or TSC2 gene leads to mTORC1 hyperactivation." (PMID 28498820, 2017). "Hyperactivation of the mTOR pathway, due to loss of function mutations in the TSC1 and TSC2 genes, upstream inhibitors of mTOR, gives rise to Tuberous Sclerosis Complex (TSC)." (PMID 28341829, 2017). "The findings yield novel insights into the molecular Tsc1+/− mouse pathology as well as the molecular effects of rapamycin treatment, which is an effective treatment for several clinical symptoms of the tuberous sclerosis complex." (PMID 28775826, 2017). "Patients with tuberous sclerosis often develop multiple tumors and it has been suggested that the TSC1 is a tumor suppressor." (PMID 28125008, 2017). "TSC1 and TSC2 are tumour suppressors whose genes have been found to be mutated in the multisystemic tumour syndrome, tuberous sclerosis." (PMID 28561026, 2017). "This same phenotype was observed in mutants for Tsc1, a mouse model for Tuberous Sclerosis syndrome, a genetic disorder with high rates of comorbid ASDs." (PMID 28448442, 2017). "About 30-40% of women with Tuberous Sclerosis Complex (TSC), a genetic disorder caused by TSC1 and TSC2 mutations, have radiographic evidence of LAM." (PMID 28410230, 2017). "Sirolimus has shown promising effects in patients with inactivating mutations in TSC1, TSC2 and STK11 in hamartoma syndromes such as tuberous sclerosis complex and Peutz-Jeghers Syndrome." (PMID 26859683, 2016). "Genetic analysis revealed a heterozygous deletion encompassing exon 1 and 2 of the TSC1 gene (tuberous sclerosis complex 1 gene), confirming the diagnosis of tuberous sclerosis complex." (PMID 27703871, 2016). "Tuberous sclerosis (TSC) is a monogenic disease resulting from defects of the tuberin (TSC2) or hamartin (TSC1) genes." (PMID 27680012, 2016). "The TSC1 (Tuberous Sclerosis 1) and TSC2 (Tuberous Sclerosis 2) genes have an important role in the aetiology of Tuberous Sclerosis Complex (TSC)." (PMID 27499730, 2016). "Examples of ASDs caused by gene mutations include fragile X syndrome (FXS) and tuberous sclerosis (TSC) which have mutations in the FMR1 and TSC1/2 genes, respectively." (PMID 26594141, 2015). "Here, we report that patient-derived fibroblasts from three monogenic models of ASD—fragile X and tuberous sclerosis TSC1 and TSC2 syndromes—display depressed Ca2+ release through inositol trisphosphate receptors (IP3Rs)." (PMID 26393489, 2015). "In the tumor syndrome tuberous sclerosis (TSC) mTOR is indirectly activated by MAPK-mediated phosphorylation of TSC1 and 2 that alleviates inhibition of mTOR." (PMID 25769101, 2015). "Loss of function of TSC1 and TSC2 leads to mTOR activation in patients with tuberous sclerosis, which has been associated with pancreatic NETs." (PMID 25092520, 2014). "Germline inactivating mutations in the TSC1 gene encoding hamartin cause tuberous sclerosis 1 (OMIM #191100), while mutations in TSC2 encoding tuberin cause tuberous sclerosis 2 (OMIM #613254)." (PMID 25513881, 2014).
tuberous sclerosis (continued). "Neurofibromatosis type 1 (NF-1) and tuberous sclerosis (TS) are autosomal dominant tumor susceptibility syndromes caused by inactivating mutations in the tumor suppressor genes NF1 and TSC1 and TSC2, respectively." (PMID 25092520, 2014). "The genes that encode these two subunits, TSC1 and TSC2, carry dominant mutations that produce tuberous sclerosis (TSC), another important syndromic form of ASD that impacts synaptic calcium signaling." (PMID 24204377, 2013). "The tumor-suppressor genes TSC1 and TSC2 are mutated in tuberous sclerosis, an autosomal dominant multisystem disorder." (PMID 23355874, 2013). "Perhaps the most important upstream regulator of mTORC1 is the tuberous sclerosis complex, composed of TSC1 (hamartin) and TSC2 (tuberin)." (PMID 24379984, 2013). "In a mouse tuberous sclerosis epilepsy model, conditional deletion of Tsc1 in astrocytes induces epilepsy commonly observed in tuberous sclerosis complex patients, and these mice survive until adulthood." (PMID 23143994, 2013). "While their genetic determinants are different (TSC1/TSC2 for tuberous sclerosis and FMR1 for fragile X syndrome), their gene products both regulate protein synthesis in neurons." (PMID 23935565, 2013). "Many of these, however, converge on the tuberous sclerosis genes TSC1 and TSC2, which produce the proteins hamartin and tuberin, respectively, and act as regulators of mTORC1." (PMID 21930185, 2012). "Overexpression of TSC1 or TSC2 led to reduction of Wnt-induced β-catenin signaling, whereas mutations in TSC1 or TSC2, as found in tuberous sclerosis patients, led to increased canonical Wnt signaling." (PMID 23083465, 2012). "Tuberous sclerosis complex (TSC) is caused by a mutation of either the Tsc1 or Tsc2 gene." (PMID 22848848, 2012). "Hyperactivation of the TOR pathway by mutations in the upstream TOR inhibitors TSC1 (tuberous sclerosis complex 1) or TSC2 promotes benign tumors and neurological and behavioral deficits, a syndrome known as tuberous sclerosis (TS)." (PMID 22319582, 2012). "In prior studies, the prevalence of sporadic tuberous sclerosis was 60-70% of the cases based on genetic (TSC1 or TSC2)." (PMID 24665269, 2012). "TSC1 and TSC2 are tumour-suppressor genes that are mutated in the tumour syndrome TSC (tuberous sclerosis complex)." (PMID 20041218, 2009). "The two major regulators of the mTORC1 cascade, TSC1 (on chromosome 9) and TSC2 (on chromosome 16), are the genes mutated in a genetic disease called Tuberous Sclerosis Complex (TSC)." (PMID 19863783, 2009). "Mutations in TSC1 or TSC2 cause tuberous sclerosis complex, but no germline mutations in TBC1D7 have been found in patients." (PMID 39901197, 2025). "Prenatal genetic testing for Tuberous Sclerosis Complex was performed in 9 cases (60%): 1 with a TSC1 mutation, 7 with TSC2 mutations, and 1 negative." (PMID 41438139, 2025). "Molecular diagnosis of tuberous sclerosis is established through the identification of a pathogenic variant of TSC1 or TSC2, regardless of the clinical findings." (PMID 39144255, 2024). "Alpha-[11C]methyl-L-tryptophan ([11C]AMT) PET shows increased tracer uptake interictally in epileptogenic tubers only of patients with tuberous sclerosis (TSC1 and TSC2) and in dysplastic cortex with an excellent agreement in seizure focus lateralization between ictal scalp EEG and [11C]AMT." (PMID 38393374, 2024). "Tuberous sclerosis TSC is an autosomal-dominant multi-system disorder that results from pathogenic variants in the tumor suppressor genes, TSC1 and TSC2, leading to aberrant activation of the mTOR pathway and often presenting with renal cysts associated with cilia disruption." (PMID 38292052, 2023). "In addition, patients with tuberous sclerosis (TSC), a genetic disorder with mutations in the Tsc1 or Tsc2, have a high prevalence of ASD." (PMID 37794488, 2023). "Due to the low prevalence of tuberous sclerosis complex in Taiwan, we do not check the genetic screening for TSC1 or TSC2 mutation." (PMID 34445268, 2021).